IL33 (interleukin 33)
Diseases named in the same sentence as IL33 in open-access papers (continued):
Sharing a sentence is not in itself a finding about the gene and the disease.
cancer (continued). "IL-33, produced from necrotic or inflamed tissues, and its ST2 receptor, are increased in patients with cancer." (PMID 32069819, 2020). "Recent studies in animal models suggest that IL-33 activates CD8+ T and NK cells and limits cancer progression." (PMID 31889095, 2019). "Hence, IL-33 could represent a substitute of IL-2 for Vγ9 T cell-based cancer immune treatments." (PMID 31652497, 2019). "Several studies have shown that IL-33, via its receptor ST2, activates various signalling pathways, including those of PI3K/AKT, MAPKs, NF-κB, JNK-cJun, and ERK1/2, to promote cancer progression." (PMID 31889095, 2019). "The administering of anti-IL-33 and anti-ST2 is effective in limiting this process and in diminishing the presence of Treg cells at the site of cancer." (PMID 31130612, 2019). "IL-33-stimulated cancer cells produce cytokines, and TME infiltrating immune cells are also involved in the expression of IL-6 in response to IL-33/ST2 signaling." (PMID 30416507, 2018). "Interleukin-33 (IL-33) and its “decoy” receptor soluble ST2 (sST2) are involved in the development of chronic inflammation and cancer." (PMID 30426271, 2018). "Active signaling by IL-33/ST2 results in activation of immune effector cells that leads to recruitment of pro- or anti-tumorigenic cells into the TME in cancer." (PMID 30205617, 2018). "While the role of IL-33/ST2 has been widely studied and established in inflammatory diseases, its role in cancer is yet to be fully elucidated." (PMID 30205617, 2018). "Together, these studies indicate that the IL-33/ST2 pathway promotes breast tumorigenesis both directly, via activation of cancer cells, and indirectly, via modulation of antitumor immunity." (PMID 28119694, 2016). "IL-33 proved signaling via the receptor-related protein of ST2L, which is widely expressed on Th cells, and mast cells and the receptor can be higher in cancer patients than in healthy controls." (PMID 27340318, 2016). "Recently, the role of the IL-33/ST2 axis in the diagnosis, prognosis, or metastasis of cancers has been described." (PMID 26456994, 2015). "Similar to IL33, TFF2 expression is lost during chronic H pylori infection in human beings, and its expression decreases progressively as cancer advances." (PMID 28210674, 2015). "The IL-33/ST2 axis has recently attracted growing attention for its diverse regulatory functions and therapeutic potential across a wide range of diseases, including cancer, fibrosis, autoimmune disorders, and central nervous system pathologies." (PMID 41268524, 2025). "Overall, we demonstrated that IL-33 plays a key role in mediating a DNA damage-resistant TME, which could represent a potential therapeutic vulnerability in chemoresistant cancer cells." (PMID 40216748, 2025). "Importantly, ILC2-activating signals, including IL-33, IL-25, and thymic stromal lymphopoietin (TSLP), also contribute to the development of an immunosuppressive microenvironment in different types of cancer." (PMID 40247153, 2025). "However, IL-33 can enhance the activity of CD8+ T cells and natural killer cells, thereby inhibiting cancer development." (PMID 40579434, 2025). "Importantly, we identify a key immune factor, IL-33, downstream of DAMP induction that significantly contributes to cancer development." (PMID 40579434, 2025). "Indeed, it has been reported that the IL-33/ILC2 axis can potentiate CD8+ T cell recruitment, activation, and proliferation in cancer settings." (PMID 39883714, 2025). "IL‐33/ST2 is a novel signaling pathway that contributes to tumorigenesis and plays a critical role in regulating angiogenesis and cancer progression in a variety of cancers." (PMID 40860436, 2025). "In summary, our work demonstrated that IL-33 plays a key role in mediating a DNA damage-resistant TME, which could represent a potential therapeutic vulnerability in targeting chemoresistant cancer cells." (PMID 40216748, 2025).
cancer (continued). "Moreover, the translational potential of the IL-33/ST2 axis as a promising immunotherapeutic target in esophageal inflammatory disorders and cancers was discussed." (PMID 40520454, 2025). "We have confirmed the correlation between IL-33 and markers like SerpinA1, SerpinA3, and EphB2 for SCC and Gli1, Gli2, FOXO3A for BCC as it highlights the complex interplay of cytokines, protease inhibitors, and receptor signaling in cancer." (PMID 39839625, 2024). "This broad involvement of IL-33 in various immune cells underscores its potential impact on nonallergic diseases, such as cancer." (PMID 38825642, 2024). "It is worth noting that the cytokines IL-33 and TNF-α, which were observed in the supernatants of the cells treated with AgNPs, have previously been documented as being produced by cancer cells undergoing apoptosis and playing a role in the signalling of dendritic and natural killer cells." (PMID 38575697, 2024). "MDSCs play a pivotal role in modulating immune responses in cancer, chronic infectious disease, and other auto-immune and pathological conditions, and were also found to play an important role in ECM and are also regulated by IL-33." (PMID 39452748, 2024). "Although these findings raise the possibility that IL-33 might promote cell migration via activating MCP-1 in various cells, the precise roles of MCP-1 on IL-33-promoted normal or cancer cell migration remain undefined." (PMID 37629196, 2023). "This significant finding is bolstered by observations that cancer relapse in patients undergoing hormone therapy is accompanied by distinctly higher serum IL-33 levels compared to patients who do not experience a relapse." (PMID 37762328, 2023). "Previous studies also demonstrated that IL-33 increased MCP-1 expression in various cells, including human and mouse mast cells, human corneal epithelial cells, human vascular endothelial cells, and human cancer cells." (PMID 37629196, 2023). "Thus, IL11-stimulated fibroblasts are primed to release IL33 when damaged to activate IL33 pathways in neighboring IL1RL1-expressing fibroblasts and other cells, which include immune cells in cancers." (PMID 36012165, 2022). "Consistent with the results of IL-33 in cancer cells, CXCR4 expression varied regardless of the invasion pattern grading score." (PMID 34298657, 2021). "Besides paracrine signaling, the CAF-induced IL-33 reciprocally enhanced the autocrine cancer-cell self-production of IL-33 and the corresponding CXCR4 upregulation, leading to the activation of SDF1/CXCR4 signaling subsequent to cancer progression." (PMID 34298657, 2021). "Therefore, IL-33/ST2 signaling can modulate immune responses to participate actively in a variety of pathological conditions, such as cancer." (PMID 34209038, 2021). "Overall, our results point to a PPARγ-driven pro-tumorigenic role of ILC2s in IL-33-dependent tumors and suggest that PPARγ targeting in ILCs may become an attractive add-on therapy for ILC2-driven diseases, including cancer." (PMID 33953160, 2021). "Similarly, in esophageal cancer, the expression of IL-33 increased the secretion of CCL2 via NF-κB, and the cancer progresses by recruiting Tregs to the cancer tissue." (PMID 34445235, 2021). "IL33 was not included because it is expressed by the cancer cells, and we therefore regard local release as more important than distant release." (PMID 33066437, 2020). "To exclude the influence of individual differences, we further analysed IL-33 expression in 64 paired HCC and adjacent para-cancer tissues in this dataset and found that it was significantly upregulated in the 44 paired HCC tissues compared with the adjacent tissues." (PMID 33308251, 2020). "The important clinicopathological parameters including histological grade, staging and periductal invasion had no statistical correlations with IL-33 in cancer cells or CAFs." (PMID 33046978, 2020).
cancer (continued). "The results revealed that KKU-055 cells expressed IL-33 intracellularly in full length form (flIL-33), but was not secreted outside the cancer cells in a mature form (mtrIL-33)." (PMID 33046978, 2020). "IL-33 appears to increase the expression of PD-1/PD-L1 and CTLA-4 molecules on certain immune cells and to improve immunotherapy efficacy of checkpoint blockade in some cancer models." (PMID 33329534, 2020). "To determine the role of IL-33 in HCC patients, we initially explored IL-33 expression in a tissue array containing 69 HCC and 64 paired adjacent normal tissue samples (five para-cancer tissue samples were damaged during the heat-induced antigen retrieval process)." (PMID 33308251, 2020). "Using these combined IL-33 cancer cells/CAFs patterns, however, there were no statistical correlations with any clinical or pathological parameters." (PMID 33046978, 2020). "Taken together, there can be no doubt that whilst IL-33 drives tumorigenesis in certain cancers and cell types much caution must be exerted surrounding future development of this cytokine as a therapeutic target." (PMID 31231372, 2019). "IL-33 can stimulate the production of pro-angiogenic factors, vascular endothelial growth factor (VEGF), and IL-8, are well-known pro-angiogenic factors in human cancers including CRC." (PMID 30547011, 2018). "To determine whether IL-33 facilitated the proliferation of CRC cells directly or via regulating other factors in vivo, we incubated primary CRC cells isolated from human cancer tissues with recombinant IL-33 protein." (PMID 30119635, 2018). "The IL-33-triggering signals in cancer cells are poorly understood because cancer cells do not always express its unique receptor ST2." (PMID 30119635, 2018). "Mechanistically, IL-33 conferred gram-negative bacteria in facilitating cancer metabolic reprograming and cancer stem cell properties." (PMID 29568370, 2018). "Knockdown of IL-33 abrogated the contribution of gram-negative bacteria to NSCLC progression by regulating cancer metabolic activities and stem cell properties." (PMID 29568370, 2018). "Interleukin-33 (IL-33) and ST2 levels and contribution in different cancers." (PMID 28119694, 2016). "IL-33-stimulated macrophages, but not non-stimulated cells significantly promoted cancer cell invasion in this in vitro invasion assay." (PMID 27150562, 2016). "A relationship between the IL-33/ST2L axis and cancer is beginning to be recognised." (PMID 26775708, 2016). "Our immunohistochemical analysis revealed that the protein expression levels of IL-33 are significantly higher in cancers than those in adjacent non-cancerous tissues and higher IL-33 expression in tumors significantly correlates with shorter five- year survival of patients." (PMID 40216748, 2025). "Extensive evidence from a variety of studies has suggested that the IL-33/ST2 axis promotes esophageal inflammation; therefore, the IL-33/ST2 axis might function as a possible biotherapeutic target for both esophageal inflammatory diseases and cancers." (PMID 40520454, 2025). "Solute factors secreted by CAFs, such as IL-6, IL-33, TGF-β, CAF-derived cardiotrophin-like cytokine factor 1 (CLCF1), and stromal cell derived factor-1 (SDF-1), can produce cancer-promoting signals and participate in the signal transduction of cancer cells and other cells within the TME." (PMID 39595654, 2024). "No statistically significant results could be seen between IL33 expression in carcinoma cells and any of the general clinicopathological characteristics." (PMID 38313904, 2024). "The IL-33 expression in carcinoma cells was negative in 44 cases (50.57%)." (PMID 38313904, 2024). "Currently, there are no clinical trials related to IL-33 or IL-25 for cancer treatment." (PMID 37455828, 2023).
cancer (continued). "In summary, macrophages could induce the activation of DLL3-dependent Notch1/Notch2 signaling, the upregulation of IL-33, and the degradation LG3BP and HSPA8, resulting in enhanced cancer-cell proliferation and elevated IL-1β, IL-12, and IL-10 secretion by macrophages." (PMID 35382168, 2022). "Next, we focused on the potential role of IL-33-responsive CD8Low and CD8High T lymphocytes during nutrient deprivation by analyzing cell surface markers such as the adenosine-converting ectoenzymes CD38 and CD39, which have been proposed as targets for cancer immunotherapy." (PMID 34504486, 2021). "Like a two-faced Janus, which faces opposite directions, IL-33/ST2 signaling may play contradictory roles on its impact on cancer progression through both immune and nonimmune cellular components." (PMID 34209038, 2021). "So far, there is no direct evidence of high extracellular IL-33 on cancer cell migration except for the studies in rat cardiac fibroblasts that revealed significant migration suppression by 1-100 ng/ml IL-33 37 and in human trophoblast choriocarcinoma cells for invasion attenuation." (PMID 33046978, 2020). "While there is now ample evidence that the IL33-MC axis is important for many cancers, the multitude of cell types in the TME able to respond to IL33 and mediated either pro- or anti-tumorigenic effects presents a formidable challenge for predicting the outcome of anti-IL33/anti-ST2 therapies." (PMID 32719677, 2020). "In all, IL-33/ST2 signaling can induce inflammatory responses that are cell-dependent and may have opposing effects in allergic or inflammatory conditions or in diseases such as cancer." (PMID 30205617, 2018). "Lastly, since the new frontier of cancer immunotherapy is the employment of immune checkpoint inhibitors (i.e., against PD-1, PD-L1, CTLA-4) further studies are needed to clarify whether IL-33 conditioning may increase the therapeutic response to checkpoint blockade in cancer patients." (PMID 30483263, 2018). "Thus, IL-33 can be used to potentiate the efficacy of cell-based anti-cancer immunotherapy without the IL-12 induced cytotoxicity." (PMID 30205617, 2018). "However, the mean expression level of IL-33 was not statistically different between in cancer and adjacent tissues (p = 0.3561)." (PMID 24778632, 2014). "However, IL-33 is upregulated in different types of inflammatory diseases and cancers, and this lack of specificity may prevent its use as a biomarker in the daily clinic diagnostic." (PMID 28119694, 2016). "Furthermore, while high levels of IL-33 in absence of common markers of inflammation may indicate the presence of cancer, it would not indicate the identity of the cancerous tissue, and more specific markers would be additionally required for diagnostics." (PMID 28119694, 2016). "Thus, depending on the cancer models used, IL-33 may or may not improve anti-PD-1 therapy." (PMID 33261061, 2020). "However, only by focusing on the IL33/MC axis, rather than studying these key regulators of immunity separately, and by utilizing novel technologies, will the full potential of targeting IL33 signaling and MC activation be discovered and exploited for anti-cancer therapies." (PMID 32719677, 2020). "Specifically, by stimulating TLR4 signaling, gram-negative bacteria induced robust IL-33 expression in NSCLC cells, facilitating cancer metabolic reprograming and development of cancer stem cell properties." (PMID 29568370, 2018). "However, no further reduction of IL-33 protein and mRNA levels were observed during progression from severe CIN to cervical cancer (CA) even though IFN-γ mRNA levels were higher in CA than in severe CIN." (PMID 30205617, 2018).
inflammation (146 papers, 2011 to 2026). Aberrant reaction of the microcirculation characterized by movement of fluid and leukocytes from the blood into extravascular tissues. "During IL-33-induced airway inflammation, IL-33 causes alveolar macrophages to change from their resting phenotype to an alternatively activated macrophage (AAM) phenotype." (PMID 38082335, 2023). "Our previous study found that Tet1 deletion enhanced HDM-induced lung inflammation in mice, and that it was linked to transcriptomic changes in proinflammatory molecules (Il33) and detoxification enzymes (Gsto1 and Aldh1a1) in total lung RNA." (PMID 35627266, 2022). "Elevated IL-33 levels were shown in patients with acute and chronic liver disease and therefore, IL-33 has been suggested as a pathogenic factor in hepatic inflammation." (PMID 31974518, 2020). "Apart from Chinese herbs and natural products, acupuncture seems to be effective in attenuating the IL-33 associated airway inflammation in an OVA-induced mouse model by reducing the serum concentrations of IL-33, sST2, and other inflammatory cytokines." (PMID 30886621, 2019). "We then administered IL-33 to these mice intranasally and monitored development of airway inflammation after transfer of Dusp10-sufficient and Dusp10-deficient Tpath2 cells." (PMID 30315197, 2018). "Compared to FRA exposed mice, Al2O3 NPs-exposed mice had higher concentrations of bronchoalveolar lavage fluid (BALF) interleukin (IL)-6 (a cytokine associated with decline in lung function) and BALF IL-33 (a cytokine induces chronic airway inflammation)." (PMID 29233151, 2017). "Our data identifies the key role of neutrophils in airway inflammation through IL-33 cleavage in the Alt-induced airway inflammation in mice, which could potentially underline the different endotypes in human disease." (PMID 34484177, 2021). "To evaluate the precise role of FABP5 in allergic lung inflammation, we intranasally administrated recombinant IL-33, one of the cytokines known to cause lung inflammation through ILC2 activation, into mice and examined lung inflammation in wild-type and Fabp5−/− mice." (PMID 33024217, 2020). "Indeed, recent studies have shown that IL-33 is released in response to particle administration and is implicated in lung inflammation after 30 days." (PMID 25497724, 2014). "To further determine whether intra-epithelial Shp2 functioned on OVA-induced airway inflammation, we examined the levels of epithelium-derived cytokines IL-25 and IL-33 in the lung tissue of OVA-sensitized Shp2-deficient or control mice 24 hours after OVA inhalation." (PMID 28481957, 2017). "Rapamycin was administered intraperitoneally during disease induction in both the IL-33–induced acute airway inflammation and bleomycin (BLM)-induced chronic fibrosis models." (PMID 40841361, 2025). "As noted, blocking the NLRP3 inflammasome with IL-33 or specific inhibitors reduced brain inflammation and significantly improved outcomes in mice." (PMID 41002937, 2025). "During H. pylori infection, gastric epithelial cell-derived IL-33 promotes TNF-α production leading to gastric inflammation and bacterial colonization." (PMID 39857676, 2025). "IL-33 orchestrates tissue remodeling and immune response in chronic airway inflammation through both TH2 (initiated by ILC2 matured by IL-33) and TH17 (via IL-1β and IL-6 derived from IL-33-matured DCs) immune responses." (PMID 39244793, 2024). "In summary, IL-33 plays a pivotal role in type 2 inflammation by engaging multiple signaling pathways and promoting the development of airway inflammation." (PMID 39301028, 2024). "In summary, this study reveals the high immunosuppressive capacity of ST2+ Tregs in immune-mediated hepatitis, which depend on intrinsic AREG as well as exogenous IL-33 for their maintenance, activation and function in liver inflammation." (PMID 38571949, 2024).